PPM1F (protein phosphatase, Mg2+/Mn2+ dependent 1F)
Diseases named in the same sentence as PPM1F in open-access papers (continued):
Sharing a sentence is not in itself a finding about the gene and the disease.
glioblastoma (1 paper, 2025). The most malignant astrocytic tumor (WHO grade IV). "To investigate, if high PPM1F levels sustain the invasive phenotype of transformed cells, we chose A172 glioblastoma cells and generated clonal PPM1F-knock-out A172 cell lines (PPM1F KO) by CRISPR/Cas9-mediated gene disruption." (PMID 40537771, 2025). "Therefore, we also included A172 glioblastoma cells in our study, which show high PPM1F expression, while integrin β1 levels are similar to MCF-7 cells." (PMID 40537771, 2025). "Genetic ablation of PPM1F completely abrogates the ability of the glioblastoma cells to invade, while re-expression of PPM1F fully restores the metastatic phenotype without modulating the proliferation of the cells." (PMID 40537771, 2025).
invasive breast carcinoma (1 paper, 2016). A carcinoma that infiltrates the breast parenchyma. "PPM1F (also call POPX2) is a serine/threonine phosphatase belonging to the protein phosphatase 2C family that is overexpressed in invasive breast cancer cells." (PMID 27769050, 2016).
metastatic melanoma (1 paper, 2020). A melanoma that has spread from its primary site to another anatomic site. "This is in line with our observation that PPM1F is expressed by malignant cells in metastatic melanomas and its expression is associated with worse prognosis." (PMID 32024530, 2020).
cancer (10 papers, 2015 to 2025). A tumor composed of atypical neoplastic, often pleomorphic cells that invade other tissues. "Some studies indicate that PPM1F expression is upregulated in cancer tissues and has an association with distant metastasis and poor survival in cancer patients." (PMID 30470261, 2018). "As constitutive PAK signaling has also been linked to cancer progression, it has been a conundrum, how the overexpression of PPM1F, a negative regulator of this kinase, could promote tumor metastasis." (PMID 40537771, 2025). "In several human cancer cell lines, PPM1F expression was directly linked to tissue invasion, which could be abrogated by PPM1F deletion." (PMID 40537771, 2025). "Together, our results demonstrate that PPM1F expression is directly linked to cancer cell invasiveness in an intact tissue and suggest that PPM1F-mediated control over integrin-dependent cell adhesion processes could promote the metastatic behaviour of tumor cells." (PMID 40537771, 2025). "Accordingly, the integrin-directed activity of PPM1F seems to promote the invasive potential of different cancer cells and unmasks a novel vulnerability of malignant tumors." (PMID 40537771, 2025). "Together, these results strongly support the notion that PPM1F overexpression can contribute to the metastatic phenotype of carcinoma cells." (PMID 40537771, 2025). "Previous studies showed that protein phosphatase Mg2+/Mn2+ dependent 1F (PPM1F) acts a dual role in cancer growth and metastasis." (PMID 30470261, 2018). "PPM1F promotes cancer cell migration and metastasis, and silencing of this gene reduces cell motility and invasiveness, but little is known about how PPM1F produces these effects." (PMID 27769050, 2016). "Studies show that PPM1F is involved in the motility and adhesion of cancer cells by regulating cytoskeleton remodeling." (PMID 26498692, 2015). "It is reported that PPM1F promote metastasis by influencing the cytoskeletal reorganization in other cancers." (PMID 26498692, 2015). "Together, our data demonstrate that PPM1F expression levels directly impact the invasive potential of cancer cells, which might be due to the role of this protein phosphatase in integrin activity regulation." (PMID 40537771, 2025). "Because AMPK acts as a central regulator of energy metabolism in cancer cells, targeting the BHLHE40‒PPM1F‒AMPK axis may represent a strategy to control cancer development." (PMID 38301894, 2024). "PPM1F has been reported to regulate cancer cell growth and metastasis 41, whereas its roles in the pathogenesis of T1DM and M1 macrophage activation remain unclear." (PMID 33042261, 2020). "Thus, PPM1F expression could be used for prognostic diagnosis or inhibited for cancer prevention and therapy." (PMID 27769050, 2016). "Thus, PPM1F expression could be used for prognostic diagnosis, or inhibited as a potential strategy for cancer prevention and therapy." (PMID 27769050, 2016). "Protein phosphatase, Mg2+/Mn2+ dependent 1F (PPM1F), a member of the PP2C family of Ser/Thr protein phosphatases, has been reported to regulate cancer cell apoptosis, proliferation and metastasis." (PMID 30470261, 2018). "Given that PPM1F controls integrin activity and matrix-dependent cell migration, it is not surprising that increased PPM1F expression has been connected to the invasive phenotype of carcinoma cells." (PMID 40537771, 2025). "The inhibitory effect of RARA could be reversed by overexpression of TXN and PPM1F in both in vivo and in vitro experiments, further highlighting the vital role of inhibiting RARA in the treatment of inducing ferroptosis in cancer." (PMID 38902322, 2024). "Because AMPK is a central regulator of energy metabolism in cancer cells, targeting the BHLHE40‒PPM1F‒AMPK axis may represent a strategy to control cancer development." (PMID 38301894, 2024).
cancer (continued). "Furthermore we analyzed the effect of miR-149 overexpression in two HCC cell lines, HepG2 and MHCC97H, on the expression of PPM1F and other putative target genes (GIT1, SP1, FOXM1) previously reported by other groups to promote migration and invasion in other cancer cell lines." (PMID 26498692, 2015).
tumor (10 papers, 2016 to 2025). "In gastric tumour samples, PPM1F has been shown to be down‐regulated, but miR‐590 is up‐regulated and the expression levels of both molecules are associated with tumour recurrence." (PMID 34907642, 2022). "The expression of PPM1F or miR-490-3p was associated with poor survival and tumor recurrence, and acted as an independent prognostic factor in patients with HCC." (PMID 30470261, 2018). "In this study, we found that the expression of PPM1F or miR-490-3p was associated with poor survival and tumor recurrence, and acted as an independent prognostic factor in patients with HCC." (PMID 30470261, 2018). "Higher PPM1F expression in tumor tissue (T>N) was also associated with smoking status in these patients (*p = 0.02)." (PMID 27769050, 2016). "In different human tumor cell types, PPM1F expression levels directly correlated with invasive potential, while deletion of PPM1F abrogates tissue invasion." (PMID 40537771, 2025). "In line with its role in integrin regulation, PPM1F is overexpressed in a number of highly motile and invasive human tumor types." (PMID 40537771, 2025). "PPM1F protein expression was also determined through IHC staining of frozen tumor sections, PPM1F expression was greater in tumor samples (indicated with a red box) than in the adjacent normal tissues (indicated with a green box)." (PMID 27769050, 2016). "Higher PPM1F mRNA expression (T>N) correlated positively with tumor size and stage (*p = 0.01 and *p = 0.02, respectively)." (PMID 27769050, 2016). "In the normal > tumor (denoted as N > T) group, the mean PPM1F mRNA level in the normal tissue was less than 2-fold greater (bar 1 vs. bar 2, *p = 0.01)." (PMID 27769050, 2016). "In the tumor > normal (denoted as T > N) group, the mean PPM1F mRNA level in the tumor tissue was 6.3-fold greater (bar 3 vs. bar 4, *p = 0.001)." (PMID 27769050, 2016). "When all cases were averaged (n = 167), the average PPM1F copy number (x 103/μg mRNA) in paired tumor tissues was 3.23-fold greater than in normal tissues (bar 1 vs. bar 2, *p = 0.005)." (PMID 27769050, 2016). "Similarly, the transcription factor BHLHE40 reportedly enhances AMPK signaling by downregulating the phosphatase PPM1F, shifting tumor metabolism from glycolysis to oxidative phosphorylation." (PMID 40806980, 2025). "Thus, the drugable enzyme PPM1F appears as an attractive novel therapeutic target to limit human tumor cell dissemination." (PMID 40537771, 2025). "With regard to the motile behaviour of tumor cells, our results suggest that the integrin-directed activity of PPM1F has a dominant function and ultimately dictates the ability of transformed cells to overcome extracellular matrix barriers and to invade into tissue." (PMID 40537771, 2025). "Moreover, our findings provide a mechanistic explanation for the correlation between PPM1F expression and an invasive phenotype of tumor cells." (PMID 40537771, 2025). "Consequently, our data support a prominent contribution of PPM1F in regulating integrin function during mammalian development and a critical function of this integrin phosphatase in tumor cell invasion." (PMID 40537771, 2025). "In addition, miR590 plays an oncogenic role through targeting PPM1F and acts as a prognostic factor for tumour recurrence." (PMID 34907642, 2022). "Taken together, our findings demonstrated that low expression of miR-490-3p or high expression of PPM1F was positively associated with poor survival and tumor recurrence in patients with HCC, and miR-490-3p suppressed cell proliferation and invasion by targeting PPM1F." (PMID 30470261, 2018).
tumor (continued). "Higher levels of PPM1F were detected in tumor tissues (T) than in normal (N) tissues." (PMID 27769050, 2016). "PPM1F mRNA expression was also greater in tumor tissues from passive smokers (n=30) than in those from non-smokers (n=28), although the fold increase was not as large as that for active smokers (bar 5 vs. bar 4;10.3-fold vs. 6.3-fold, difference = 4.0-fold, 95% CI = 2.4 to 5.6-fold, *p = 0.026)." (PMID 27769050, 2016). "Similarly, the PPM1F KO cells re-expressing PPM1F were found to penetrate the ectoderm and were reaching blood vessels, while A172 cells devoid of PPM1F stayed on top of the ectoderm, where they formed a single micro-tumor entity (open arrowhead)." (PMID 40537771, 2025). "Tumor xenografts were generated with NC, RARA-SH1, NC + TXN-OE + PPM1F-OE, and RARA-SH1 + TXN-OE + PPM1F-OE cell lines." (PMID 38902322, 2024). "To confirm the positive contribution of PPM1F to an invasive tumor phenotype in an intact tissue, we employed the chicken chorioallantoic membrane (CAM) assay, which monitors tissue infiltration by human tumor cells over the course of several days." (PMID 40537771, 2025). "Furthermore, in both monotherapy and combination groups, RARA knockdown resulted in reduced tumor volume and weight, an effect that was reversed by overexpression of TXN and PPM1F, which was consistent with vitro experiments." (PMID 38902322, 2024). "PPM1F mRNA expression was greater in tumor tissues from active smokers (n=7) than in those from non-smokers (n=28) (bar 6 vs. bar 4; 12.8-fold vs. 6.3-fold, difference = 6.5-fold, 95% CI = 2.5 to 10.5-fold, *p = 0.01)." (PMID 27769050, 2016). "We examined the expression levels of PPM1F in multiple gastrointestinal tumors using the TCGA database and found that PPM1F had the most obvious upregulation in paired (n = 50, P < 0.0001; Fig. 1a1) and unpaired HCC tissues (n = 372, P < 0.0001; Fig. 1a2) as compared with the other tumor tissues." (PMID 30470261, 2018).
PPM1F also shares sentences with these, for which no sentence is quoted: adenocarcinoma (1 paper); cardiac hypertrophy (1); cervical cancer (1); colon carcinoma (1); colorectal adenocarcinoma (1); cyst (1); gastrointestinal tumors (1); heart diseases (1); heart failure (1); hypertrophy (1); left ventricular hypertrophy (1); liver fibrosis (1); lung adenocarcinoma (1); ovarian carcinoma (1); Periventricular heterotopia (1); promyelocytic leukemia (1); renal carcinoma (1); renal cysts and diabetes syndrome (1); schizophrenia (1); testicular germ cell tumor (1); type 1 diabetes mellitus (1).